TEDDM1 (transmembrane epididymal protein 1)
Synonyms: He9; Epdd1; TMEM45C; EDDM9; HEL-S-45e
Tractability: Antibody: UniProt predicts a signal peptide or a membrane-spanning region.
Gene: Protein-coding gene on chromosome 1 (182,398,117 to 182,400,667, reverse strand). Ensembl gene ENSG00000203730.
Subcellular location: Membrane
Gene Ontology:
Cellular component: membrane
Genetic constraint (gnomAD): Loss-of-function variants: 0 observed, 1.01 expected, observed/expected ratio (o/e) 0, 90% interval 0 to 1.72. That is too few expected variants to judge how well the gene tolerates losing a copy. Missense variants: 344 observed, 336.33 expected, observed/expected ratio (o/e) 1.02, 90% interval 0.94 to 1.12. Synonymous variants: 126 observed, 134.31 expected, observed/expected ratio (o/e) 0.94, 90% interval 0.81 to 1.09.
Homologues: Orthologues: chimpanzee TEDDM1 (98% identical), macaque TEDDM1 (95% identical), pig TEDDM1 (71% identical), mouse Teddm1b (70% identical), rat Teddm1b (68% identical), mouse Teddm1a (68% identical), rat Teddm1a (67% identical), tropical clawed frog teddm1 (25% identical). Paralogues in human: TMEM45A (25% identical), TMEM45B (18% identical).
Diseases named in the same sentence as TEDDM1 in open-access papers:
TEDDM1 is named in the same sentence as 1 disease in open-access papers, as found by Europe PMC text mining. Sharing a sentence is not in itself a finding about the gene and the disease.
TEDDM1 shares sentences with these, for which no sentence is quoted: COVID-19 (1 paper).